ACTR8 (actin related protein 8)
Description:
Plays an important role in the functional organization of mitotic chromosomes. Exhibits low basal ATPase activity, and unable to polymerize. Proposed core component of the chromatin remodeling INO80 complex which is involved in transcriptional regulation, DNA replication and probably DNA repair. Required for the recruitment of INO80 (and probably the INO80 complex) to sites of DNA damage. Strongly prefer nucleosomes and H3-H4 tetramers over H2A-H2B dimers, suggesting it may act as a nucleosome recognition module within the complex.
Synonyms: hArp8; ARP8; INO80N
Tractability: Small molecule: a structure with a bound ligand is known. PROTAC: ubiquitination databases record sites on it; its protein half-life has been measured.
Gene: Protein-coding gene on chromosome 3 (53,863,038 to 53,882,198, reverse strand). Ensembl gene ENSG00000113812.
Subcellular location: Nucleus; Chromosome
Subcellular location (Human Protein Atlas): Nucleoplasm; Centrosome
Pathways (Reactome):
DNA Repair: DNA Damage Recognition in GG-NER
Metabolism of proteins: UCH proteinases
Gene Ontology:
Molecular function: protein binding; mRNA binding
Biological process: chromatin remodeling; positive regulation of DNA-templated transcription; regulation of cell cycle; regulation of chromosome organization; regulation of DNA replication; regulation of DNA strand elongation; double-strand break repair; regulation of DNA-templated transcription; positive regulation of DNA repair; positive regulation of telomere maintenance in response to DNA damage; regulation of DNA metabolic process; regulation of DNA repair; regulation of embryonic development; telomere maintenance
Cellular component: Ino80 complex; nucleoplasm; nucleus; chromosome
Genetic constraint (gnomAD): Loss-of-function variants: 58 observed, 69.84 expected, observed/expected ratio (o/e) 0.83, 90% interval 0.67 to 1.03. The upper end of that interval is the gene's LOEUF score, 1.03, which puts it in group 4 of 6, group 1 being the genes least tolerant of losing a copy. Missense variants: 594 observed, 692.49 expected, observed/expected ratio (o/e) 0.86, 90% interval 0.8 to 0.92. Synonymous variants: 234 observed, 246.91 expected, observed/expected ratio (o/e) 0.95, 90% interval 0.85 to 1.06.
Homologues: Orthologues: chimpanzee ACTR8 (99% identical), macaque ACTR8 (99% identical), guinea pig ACTR8 (99% identical), pig ACTR8 (99% identical), dog ACTR8 (98% identical), rabbit ACTR8 (98% identical), mouse Actr8 (97% identical), rat Actr8 (90% identical), zebrafish actr8 (75% identical), tropical clawed frog actr8 (72% identical), Drosophila melanogaster Arp8 (33% identical). Paralogues in human: ACTG1 (19% identical), ACTB (19% identical), ACTA2 (18% identical), ACTBL2 (18% identical), ACTG2 (18% identical), ACTA1 (18% identical), ACTC1 (18% identical), ACTR1B (18% identical), ACTRT3 (17% identical), ACTR1A (16% identical), ACTRT2 (15% identical), ACTR2 (15% identical), and 14 more.
Diseases named in the same sentence as ACTR8 in open-access papers:
ACTR8 is named in the same sentence as 8 diseases in open-access papers, as found by Europe PMC text mining. Sharing a sentence is not in itself a finding about the gene and the disease. The quoted sentences say what the papers report.
cancer (1 paper, 2022). A tumor composed of atypical neoplastic, often pleomorphic cells that invade other tissues. "ACTL6A, CHD2, and ACTB had the highest pan‐cancer G‐score for amplification, whereas CHD5, SHPRH, INO80, and ACTR8 had the highest pan‐cancer G‐score for deletions." (PMID 35789070, 2022).
ACTR8 also shares sentences with these, for which no sentence is quoted: breast carcinoma (1 paper); colon cancer (1); colorectal cancer (1); infection (1); lung carcinoma (1); ovarian carcinoma (1); prostate carcinoma (1).